MYL9 (myosin light chain 9)
Diseases named in the same sentence as MYL9 in open-access papers (continued):
Sharing a sentence is not in itself a finding about the gene and the disease.
cancer (continued). "We examined whether myosin regulatory light polypeptide 9 (MYL9) regulates cancer cell proliferation." (PMID 34821071, 2022). "Nevertheless, studies on the association between MYL9 expression and cancer are rare, and there has been no published report on the characteristics of MYL9 expression and its clinical significance in ESCC." (PMID 28388691, 2017). "Both of these subtypes shared characteristics of myofibroblast cancer-associated fibroblasts (mCAFs) because of the high level of expression of the genes encoding extracellular matrix building, i.e., COL4A1; ECM remodeling proteins, i.e., MMP11; and contractile proteins, i.e., TPPP3 and MYL9." (PMID 39796089, 2024). "The role of MYL9 phosphorylation may differ, based on the type of cancer." (PMID 34821071, 2022). "However, the expression of MYL9 in cancer cells is controversial." (PMID 34974798, 2022). "Therefore, the effects of MYL9 phosphorylation appear to depend on the type of cancer cell." (PMID 28388691, 2017). "However, MYL9 expression levels in cancer cell cytoplasm varied widely among ESCC specimens." (PMID 28388691, 2017). "Cytoskeletal regulators (MYL9, TAGLN) and transcription factors (SNAI2) promote EMT and cancer stemness, while PMEPA1, IL6, IL8, IGFBP3, INHBA, and VEGFA contribute to proliferation, angiogenesis, and immune modulation." (PMID 41009714, 2025). "The top enriched pathways for the upregulated genes included focal adhesion, regulation of actin cytoskeleton and pathway in cancer, as well as the key upregulated genes included LAMC1, MYL9, COL1A, and KAT2A which, regulate ECM formation and actin skeleton." (PMID 39735192, 2024). "Studies have shown that upregulation of MYL9 and ACTA2 promotes migration in most cancers, but their downregulation promotes migration in a few cancers." (PMID 37251946, 2023). "MYL9 has the potential to become a molecular marker for diagnosing PRAD and predicting cancer progression and prognosis." (PMID 35909899, 2022). "However, it is still unclear whether MYL9 regulates cancer‐cell invasion." (PMID 34821071, 2022). "Additionally, we also consider that the expressions of MYL9 and CNN1 are downregulated in CRC because of the general dedifferentiation of cancer cells, but those cancer cells with higher expression of MYL9 and CNN1 may be better suited for migration and metastasis compared with lower expressed ones." (PMID 32127961, 2020). "We identified six genes including UNG, FUCA2, DERA, GMFB, TF, and SNX24 as significantly downregulated and two genes including MYL9 and TAGLN as significantly upregulated upon mir-145 over-expression in distinct cancer types." (PMID 27655328, 2016). "Genes such as KIF5A, SOX10, MYL9, TRIM9, MYH11, and SNAP25 are known to play important roles in biological development, suggesting that LRP1B may also be a key factor in cancer." (PMID 40170839, 2025). "MYL9 can combine with YAP1, a vital regulator of the HIPPO pathway that is crucial for promoting cancer development, especially in CRC, to activate HIPPO signaling and promote the proliferation of cancer cells." (PMID 39768172, 2024). "Since that MYL9 contributes to the stiffer matrix and leads to Src activation, and Src is a well-known upstream driver of YAP in cancer metastasis, we supposed that the PRPF19/MYL9 may regulate the Src/YAP pathway in CRC." (PMID 37031206, 2023). "Whether MYL9 plays a role in the TME and immunotherapy response in cancer requires further investigation." (PMID 37926835, 2023). "As a result, we found that MYL9 and CNN1 may participate in “pathways in cancer”, “calcium signaling pathway” and “focal adhesion”." (PMID 32127961, 2020). "Other predicted blood-secretory marker proteins such as PAICS, CHRDL1, KLF2, COL10A1 and MYL9 have not heretofore been reported to be cancer related." (PMID 21060876, 2010).
infection (6 papers, 2016 to 2025). The state of being infected such as from the introduction of a foreign agent such as serum, vaccine, antigenic substance or organism. "In the studied cohort, a higher Myl9 level at 6 months after infection was correlated with a higher blood neutrophil count." (PMID 39879907, 2025). "The high-Myl9 group presented significant residual respiratory symptoms at 6 months post-infection (p < 0.05)." (PMID 39879907, 2025). "After adjusting for cell composition, only one gene, myosin light chain 9 (MYL9), remained differentially expressed between early and late season infections, with a higher expression in late season infections." (PMID 39162546, 2024). "•The neutrophil count is correlated with the Myl9 level at 6 months after infection." (PMID 39879907, 2025). "As a myosin molecule, MYL9 has diverse roles in different cell types, and can interact with the T cell activation marker CD69 to induce inflammation during infections." (PMID 39162546, 2024). "The genes significantly impacted by infection only in CS included mast cell proteinase-3, γ-glutamyltransferase 5 (GGT5), CD163 as well as those involved in smooth muscle contraction, such as tropomyosin (TPM2), myosin, light chain 9, regulatory (MYL9), and calponin 1, basic, smooth muscle (CNN1)." (PMID 27197554, 2016).
adenocarcinoma (1 paper, 2016). A common cancer characterized by the presence of malignant glandular cells. "One examples is MYL9, which is higher expressed in adenocarcinoma on transcriptomic and proteomic level, but while the protein expression was significantly different, the mRNA significance value not significant (p = 0.1)." (PMID 26930711, 2016).
MYL9 also shares sentences with these, for which no sentence is quoted: bladder cancer (5 papers); head and neck squamous cell carcinoma (4); melanoma (3); cholangiocarcinoma (2); colon adenocarcinoma (2); dilated cardiomyopathy (2); glioblastoma (2); glioma (2); liver cancer (2); squamous cell carcinoma (2); acute kidney injury (1); aortic coarctation (1); arrhythmogenic right ventricular cardiomyopathy (1); bladder urothelial carcinoma (1); blood cancer (1); brain glioma (1); cardiac disease (1); cardiovascular disease (1); cervical lymphadenitis (1); chordoma (1); coronary artery aneurysms (1); craniosynostosis (1); Crohn disease (1); endocrine disorder (1); endometriosis (1); Epstein-Barr virus infection (1); human papillomavirus infection (1); hydronephrosis (1); inflammatory bowel disease (1); interstitial lung disease (1).
A further 21 diseases each share a sentence with MYL9 in 1 paper.